SMC1A (structural maintenance of chromosomes 1A)
Description:
Involved in chromosome cohesion during cell cycle and in DNA repair. Central component of cohesin complex. The cohesin complex is required for the cohesion of sister chromatids after DNA replication. The cohesin complex apparently forms a large proteinaceous ring within which sister chromatids can be trapped. At anaphase, the complex is cleaved and dissociates from chromatin, allowing sister chromatids to segregate. The cohesin complex may also play a role in spindle pole assembly during mitosis. Involved in DNA repair via its interaction with BRCA1 and its related phosphorylation by ATM, or via its phosphorylation by ATR.
Synonyms: DXS423E; KIAA0178; SB1.8; SMC1; SMC1L1; Smcb; CDLS2; DEE85; EIEE85; SMC1alpha
Tractability: Small molecule: a structure with a bound ligand is known. PROTAC: UniProt records ubiquitination sites on it; ubiquitination databases record sites on it; its protein half-life has been measured; a small molecule that binds it is known.
Gene: Protein-coding gene on chromosome X (53,374,149 to 53,422,728, reverse strand). Ensembl gene ENSG00000072501.
Subcellular location: Nucleus; Chromosome; Chromosome, centromere, kinetochore
Subcellular location (Human Protein Atlas): Nucleoplasm; Cytosol
Pathways (Reactome):
Cell Cycle: Cohesin Loading onto Chromatin; Establishment of Sister Chromatid Cohesion; Resolution of Sister Chromatid Cohesion; Separation of Sister Chromatids
Metabolism of proteins: SUMOylation of DNA damage response and repair proteins
Reproduction: Meiotic synapsis
Signal Transduction: Estrogen-dependent gene expression
Gene Ontology:
Molecular function: chromatin binding; protein binding; protein heterodimerization activity; RNA binding; DNA binding; ATP binding; ATP hydrolysis activity; mediator complex binding
Biological process: mitotic spindle assembly; response to DNA damage checkpoint signaling; response to radiation; sister chromatid cohesion; DNA repair; establishment of mitotic sister chromatid cohesion; meiotic cell cycle; mitotic sister chromatid cohesion; mitotic sister chromatid segregation; chromosome organization
Cellular component: cohesin complex; cytosol; kinetochore; meiotic cohesin complex; mitotic cohesin complex; mitotic spindle pole; nuclear matrix; nucleoplasm; nucleus; chromosome; chromosome, centromeric region; condensed nuclear chromosome
Gene-disease validity (ClinGen):
ClinGen rates the evidence that SMC1A causes each of these diseases.
X-linked complex neurodevelopmental disorder (X-linked): Definitive. A complex neurodevelopmental disorder that is transmitted via X-linked inheritance, and is characterized by intellectual disability, autism and epilepsy.
Homologues: Orthologues: chimpanzee SMC1A (100% identical), macaque SMC1A (100% identical), dog SMC1A (99% identical), mouse Smc1a (99% identical), rat Smc1a (99% identical), pig SMC1A (98% identical), guinea pig SMC1A (97% identical), tropical clawed frog smc1a (95% identical), zebrafish smc1al (90% identical), zebrafish smc1a (89% identical), Caenorhabditis elegans citk-2 (15% identical), Caenorhabditis elegans citk-1 (14% identical). Paralogues in human: SMC1B (54% identical), SMC4 (22% identical), SMC2 (20% identical), SMC3 (19% identical), CKAP4 (8% identical), CCDC157 (8% identical), CCDC122 (4% identical).
Diseases named in the same sentence as SMC1A in open-access papers:
SMC1A is named in the same sentence as 106 diseases in open-access papers, as found by Europe PMC text mining. Sharing a sentence is not in itself a finding about the gene and the disease. The quoted sentences say what the papers report.
Cornelia de Lange syndrome (75 papers, 2008 to 2026). A rare syndrome characterized by low birth weight, delayed growth, intellectual disabillity, behavioral problems, and a distinctive facial appearance (thin, arched eyebrows, low set ears, small teeth, and small nose). "SMC1A is a gene in which pathogenic alterations are seen in about 5% of patients with Cornelia de Lange Syndrome (CdLS)." (PMID 41180190, 2025). "Variants in the SMC1A gene have been associated with Cornelia de Lange syndrome (CdLS) (MIM #300590), in resembling the Rett syndrome (RTT) phenotype, intellectual disability, and developmental and epileptic encephalopathy (DEE)." (PMID 41153413, 2025). "SMC1A pathogenic variants have been associated with Cornelia de Lange syndrome, but, at both extremes of the spectrum, severe cases with early onset epilepsy/EE or mildly affected patients are described." (PMID 33919646, 2021). "Mutations in SMC1A have been shown to cause Cornelia de Lange syndrome, a multisystem developmental disorder with defects ranging from limb formations to cardiac, gastrointestinal, growth and cognitive systems." (PMID 24699359, 2014). "Mutation and deregulation of SMC1A are highly relevant to diverse human diseases, including Cornelia de Lange syndrome and malignant carcinomas." (PMID 23426528, 2013). "Mutations in SMC1A cause the X-linked form of Cornelia de Lange syndrome, in which approximately 25% of patients have CHD, including LS-CHD." (PMID 22969434, 2012). "Germline mutations in the NIPBL gene with an autosomal dominant pattern and in the SMC1A gene with an X-linked pattern have been identified in Cornelia de Lange syndrome." (PMID 21707975, 2011). "In addition to the duplication, point mutation in SMC1A was shown to be associated with Cornelia de Lange syndrome with facial dysmorphism, mental retardation and growth deficit in childhood." (PMID 25637059, 2015). "Pathogenic variants in SMC1A are often dominant-negative and cause Cornelia de Lange syndrome (CdLS)." (PMID 38612920, 2024). "The SMC1A gene mutation was first described in a patient with rare Cornelia de Lange syndrome (CdLS), characterized by growth retardation and typical facial deformities." (PMID 38440111, 2024). "Cornelia de Lange syndrome (CdLS) has seven disease-associated genes; two of them localize (SMC1A and SMC3) to cilia and two of them (ANKRD11 and HDAC8) are implicated in cilia." (PMID 37542408, 2023). "Pathogenic variants in SMC1A as well as other cohesin subunit-encoding and cohesin regulatory protein-encoding genes, can often cause Cornelia de Lange syndrome (CdLS), a developmental condition involving multiple systems." (PMID 37107610, 2023). "Exome reanalysis identified a hemizygous likely pathogenic variant in the SMC1A gene, consistent with Cornelia de Lange syndrome 2 (CdLS)." (PMID 35937981, 2022). "SMC1A variants are known to cause Cornelia de Lange Syndrome (CdLS) which encompasses a clinical spectrum of intellectual disability, dysmorphic features (long or thick eyebrows, a hypomorphic philtrum and small nose) and, in some cases, epilepsy." (PMID 35712061, 2022). "In humans, mutations in SMC1A are among the cohesin (or cohesin regulator) mutations that cause Cornelia de Lange syndrome (CdLS), a rare multifactorial developmental disorder that includes craniofacial abnormalities." (PMID 34943067, 2021). "The most common cohesinopathy, Cornelia de Lange syndrome, is caused by dysfunction in a variety of cohesin subunits, such as NIPBL, SMC1A, SMC3, RAD21, BRD4, HDAC8, and ANKRD11." (PMID 40943870, 2025). "A number of mutations that cause Cornelia de Lange Syndrome [CDLS2 (MIM: 300590)] have been mapped to the gene encoding the core cohesin subunit, SMC1A, which encodes the SMC1A protein." (PMID 37650609, 2023). "The major causative genes of the Cornelia de Lange Syndrome are NIPBL, SMC1A, SMC3, RAD21 and HDAC8." (PMID 34827619, 2021).
Cornelia de Lange syndrome (continued). "Cornelia de Lange syndrome (CdLS) results from autosomal dominant or X-linked mutations in NIPBL, SMC1A, SMC3, RAD21 or HDAC8." (PMID 31935221, 2020). "Cornelia de Lange syndrome (CdLS), a rare, multisystemic disorder, has been linked to genetic alterations in NIPBL, SMC1A, SMC3, HDAC8, and RAD21 genes." (PMID 30606125, 2019). "Mutations in RAD21, SMC1α and SMC3 have been shown to result in Cornelia de Lange syndrome, which causes intellectual disability and growth retardation and as well as facial and limb anomalies." (PMID 24992337, 2014). "For example, in a previous work of our group focusing on Cornelia de Lange syndrome, the computational modeling of ATP hydrolysis in the head domain of the SMC1A and SMC3 proteins was able to illustrate the changes associated with a pathogenic variant in SMC3 that functionally alters this mechanism." (PMID 38279279, 2024). "Growth retardation, craniofacial anomalies, microbrachycephaly and reduced body fat have been described in cohesinopathies such as Cornelia de Lange syndrome CdLS, which is inherited in an autosomal dominant (NIPBL, SMC2 or RAD21) or X‐linked (SMC1A or HDAC8) pattern." (PMID 36627765, 2023). "In the SMC1A gene, known as a causative gene of Cornelia de Lange syndrome, an LPV (c.2368C>T;p.Arg790Trp) was identified in a male sibling pair (M-055-P, M-055-S) clinically suspected of Cornelia de Lange syndrome." (PMID 33584783, 2020). "Cornelia de Lange syndrome (CdLS), the best characterized cohesinopathy, is caused by mutations of cohesin regulators, such as NIPBL and HDAC8, or of cohesin subunits, including SMC1A, SMC3, and RAD21." (PMID 33262685, 2020). "Because WDSTS can phenotypic overlap with Pierpont syndrome, Cornelia De Lange syndrome and Kabuki syndrome, the candidate genes causing the later three syndromes (i.e. TBL1XR1, NIPBL, SMC1A, SMC3, RAD21, HDAC8, KMT2D, and KMD6A) in our cohort have been excluded." (PMID 30305169, 2018). "For example, the DDD study reported marked differences between missense and LGD mutations in the Cornelia de Lange syndrome gene SMC1A, noting that individuals with LGD DNMs lack the characteristic facial dysmorphia observed in individuals with missense Cornelia de Lange syndrome-causing DNMs." (PMID 29179772, 2017). "Pathogenic variants in NIPBL, MAU2, SMC1A, SMC3, RAD21, and HDAC8 cause Cornelia de Lange syndrome (CdLS), a multisystem disorder characterized by intellectual disability, facial dysmorphism, growth delay, and upper limb anomalies." (PMID 41492387, 2025). "Cornelia de Lange Syndrome (CdLS) is a genetically heterogeneous disorder predominantly caused by De Novo heterozygous pathogenic variants in NIPBL (80% of cases), with less frequent involvement of SMC1A (5%), HDAC8 (4%), SMC3 (1–2%), RAD21 (<1%), and BRD4 (<1%)." (PMID 40700109, 2025). "Surprisingly, DNA methylation analyses revealed a DNA methylation profile similar to the Cornelia de Lange syndromes 1–4 (CdLS) episignature, associated with variants in NIPBL, SMC1A, SMC3, and RAD21." (PMID 38273166, 2024). "Cornelia de Lange syndrome (CdLS, OMIM # 122470, #614701, #610759, #300590, and #300882) is a rare genetic disorder caused by variants in cohesion complex genes including NIPBL (NM_133433.3), SMC1A (NM_006304.4), SMC3 (NM_005445.3), HDAC8 (NM_018486.2), and RAD21 (NM_006265.3)." (PMID 35935361, 2022). "Cornelia de Lange syndrome (CdLS) is the most prominent cohesinopathy and arises from heterozygous mutations, usually in the gene encoding cohesin regulator NIPBL, but sometimes in genes encoding the core mitotic-specific subunits of cohesin (RAD21, SMC3 and SMC1A) and the SMC3 deacetylase HDCA8." (PMID 34202641, 2021). "Mutations in core cohesin subunits SMC1A, SMC3 and RAD21, or their regulators NIPBL and HDAC8, cause Cornelia de Lange syndrome (CdLS)." (PMID 26581180, 2015).
Cornelia de Lange syndrome (continued). "Cornelia de Lange Syndrome (CdLS), on the other hand, is caused by haploinsufficiency for NIPBL or by missense mutations in the SMC1A or SMC3 cohesin subunits." (PMID 21637801, 2011). "Variants in genes encoding various structural or functional components of the cohesin complex, including RAD21, SMC1A, SMC3, BRD4, STAG1/2, NIPBL, HDAC8, WAPL, ANKRD11 and in single individuals PDS5A and ESPL1, have been implicated in Cornelia de Lange Syndrome (CdLS)." (PMID 32193685, 2020). "Genetic alterations of NIPBL, SMC1A, SMC3, HDAC8, and RAD21 genes are believed to trigger the development of Cornelia de Lange syndrome." (PMID 30606125, 2019). "However, after conducting whole exome sequencing analysis, no genetic variants associated with Cornelia de Lange syndrome, such as NIPBL, SMC1A, SMC3, RAD21 and HDAC8 were found." (PMID 38348454, 2024). "Heterozygous mutations in the cohesin regulator NIPBL or cohesin structural components SMC1A and SMC3 result in the multisystem developmental disorder Cornelia de Lange Syndrome (CdLS)." (PMID 19468298, 2009).
colorectal cancer (18 papers, 2013 to 2025). A primary or metastatic malignant neoplasm that affects the colon or rectum. "In colorectal cancer, mutations and aberrant expression of SMC1A have been shown to be involved in tumor development." (PMID 39851557, 2025). "This is supported by the finding that SMC1A mutations have been identified in human cancers characterized by genome instability, such as colorectal cancer." (PMID 39682772, 2024). "In colorectal cancers, SMC1A was present as extra-copies, mutations, and overexpression, and it contributes to cancer development and metastasis." (PMID 37537540, 2023). "SMC1A mutations and overexpression have previously been associated with colorectal cancer aggression." (PMID 33473169, 2021). "Here we showed that SMC1A cohesin core gene was present as extra-copies, mutated, and overexpressed in human colorectal carcinomas." (PMID 30823889, 2019). "This study aims to evaluate the functional role of SMC1A in colorectal cancer (CRC) both in vitro and in vivo, and the underlying molecular mechanisms." (PMID 25884313, 2015). "PARP mediates replication fork stability in response to stress and we recently showed that depletion of the cohesin SMC1A, which is mutated in colorectal cancer, sensitizes cells to selective killing by PARP inhibition." (PMID 23390603, 2013). "Previously we showed that SMC1A mutations decrease from early adenomas to colorectal cancers." (PMID 30823889, 2019). "Overexpression of SMC1A was identified as a predictor of poor prognosis in late-stage colorectal cancer." (PMID 39851557, 2025). "Previous studies have established that SMC1A is involved in cancer development and in particular, is overexpressed in chromosomally unstable human colorectal cancer (CRC)." (PMID 38365745, 2024). "Another study showed that SMC1A knockdown significantly inhibited the cell proliferation and activation of Akt in colorectal cancer." (PMID 37212524, 2023). "Instead, somatic mutations in the NIPBL, RAD21, SMC1A, SMC3 and STAG2 genes have been described in many human cancers including acute myeloid leukemia, bladder, and colorectal cancer." (PMID 30823889, 2019). "Additionally, SMC1A overexpression was identified as an independent poor prognostic predictor in advanced colorectal cancers." (PMID 37537540, 2023). "Another study revealed that colorectal cancer cells could recruit circulating CAFs, and high SMC1A expression levels in colorectal cancer cells promoted this recruitment." (PMID 31413760, 2019). "Moreover, down regulation of SMC1A in lung adenocarcinoma cells and colorectal cancer cells induced apoptosis." (PMID 28868238, 2017). "Moreover, SMC1A was proved to play an important role in colorectal cancer metastasis by stimulating inflammatory mediators." (PMID 28868238, 2017).
Intellectual disability (12 papers, 2014 to 2025). "DEE is characterized by refractory seizures, developmental delay, or intellectual disability, which may be caused by gene mutation, also including the SMC1A gene." (PMID 41153413, 2025). "Also, we discuss how somatic mosaicism and epigenetic variability underlie the clinical diversity of SMC1A-associated epilepsy and systematically describe the entire phenotypic spectrum, from early-onset, therapy-resistant seizures to milder intellectual disability profiles." (PMID 41153413, 2025). "Epileptic encephalopathy, intellectual disability of different grades, and stereotypic movements have also been reported in several patients with likely RTT due to SMC1A variants." (PMID 41153413, 2025). "Skewed XCI of the XCI-escaping genes DDX3X and SMC1A were revealed in intellectual disability female patients." (PMID 31781162, 2019).
epilepsy (10 papers, 2020 to 2025). A brain disorder characterized by episodes of abnormally increased neuronal discharge resulting in transient episodes of sensory or motor neurological dysfunction, or psychic dysfunction. "Both missense and truncating SMC1A variants have been reported in patients with early-onset, therapy-refractory epilepsy and severe neurodevelopmental impairment." (PMID 41153413, 2025). "Epigenetic differences between tissues (e.g., brain vs. blood) likely explain why some individuals with the same SMC1A mutation suffer from severe epilepsy while others only show mild cognitive impairment." (PMID 41153413, 2025). "The downregulation of smc1a impaired neuronal development in zebrafish, and mutations of this gene were found in patients with epilepsy." (PMID 32455839, 2020). "In addition, heterozygous truncation mutations of the SMC1A gene are detected in cases of severe early-onset epilepsy with cluster seizures in females." (PMID 41153413, 2025). "More recently, SMC1A truncating variants have been described as the cause of a neurodevelopmental disorder with early-childhood onset drug-resistant epilepsy with seizures that occur in clusters, similar to that seen in PCDH19-related epilepsy, but without the classical features of CdLS." (PMID 35712061, 2022). "In contrast, skewing toward the mutant allele or a random XCI pattern can produce a higher proportion of cells with reduced functional SMC1A, driving more severe neurological manifestations, including early-onset, treatment-resistant epilepsy." (PMID 41153413, 2025). "SMC1A variants are also detected in patients with encephalopathy with epilepsy who do not resemble CdLS." (PMID 41153413, 2025). "We know of no previous reports of SMC1A gene variant phenotypes in infants in whom bathing epilepsy characterized their first epileptic episode." (PMID 38440111, 2024). "Interestingly, SMC1A-DEE and PCDH19 clustering epilepsy share some epilepsy-related features, e.g., drug resistance and seizure clustering." (PMID 37107610, 2023). "Indeed, subsequent WES analysis of this patient revealed pathological de novo mutation in the SMC1A gene (data not shown), hence the functional study of this variant indicated the misdiagnosed problem of SCN1A-related epilepsies." (PMID 32581296, 2020). "Differential SMC1A insufficiency in SMC1A-DEE individuals with random XCI could further lead to cellular interference (i.e., interference between cells with differential levels of SMC1A) at tissue levels, similar to the proposed for the etiology of PCDH19 clustering epilepsy." (PMID 37107610, 2023).